OR2M7 (olfactory receptor family 2 subfamily M member 7)
Description:
Odorant receptor.
Synonyms: OR1-58
Tractability: Antibody: its Gene Ontology location is reachable by antibodies, with high confidence; UniProt places it where antibodies can reach, with medium confidence; UniProt predicts a signal peptide or a membrane-spanning region.
Gene: Protein-coding gene on chromosome 1 (248,323,630 to 248,324,568, reverse strand). Ensembl gene ENSG00000177186.
Subcellular location: Cell membrane
Pathways (Reactome):
Sensory Perception: Expression and translocation of olfactory receptors; Olfactory Signaling Pathway
Gene Ontology:
Molecular function: olfactory receptor activity; G protein-coupled receptor activity
Biological process: detection of chemical stimulus involved in sensory perception of smell; G protein-coupled receptor signaling pathway
Cellular component: plasma membrane; membrane
Genetic constraint (gnomAD): Loss-of-function variants: 0 observed, 0.21 expected, observed/expected ratio (o/e) 0, 90% interval 0 to 1.88. That is too few expected variants to judge how well the gene tolerates losing a copy. Missense variants: 390 observed, 394.5 expected, observed/expected ratio (o/e) 0.99, 90% interval 0.91 to 1.08. Synonymous variants: 129 observed, 135.26 expected, observed/expected ratio (o/e) 0.95, 90% interval 0.83 to 1.1.
Homologues: Orthologues: chimpanzee OR2M7 (99% identical), dog OR2M9 (77% identical). Paralogues in human: OR2M5 (93% identical), OR2M2 (92% identical), OR2M3 (92% identical), OR2M4 (73% identical), OR2T33 (56% identical), OR2T8 (55% identical), OR2T12 (55% identical), OR2V2 (53% identical), OR2T2 (52% identical), OR2T35 (52% identical), OR2V1 (52% identical), OR2L3 (52% identical), and 80 more.